PDK1 (pyruvate dehydrogenase kinase 1)
Diseases named in the same sentence as PDK1 in open-access papers (continued):
Sharing a sentence is not in itself a finding about the gene and the disease.
Hyperinsulinemia (1 paper, 2021). An increased concentration of insulin in the blood. "In agreement with hyperinsulinemia in HFD mice, elevated expressions of IR, insulin receptor substrate 2 (IRS-2), phosphoinositide 3-kinase (PI3K), phosphoinositide-dependent kinase-1 (PDK1), and PPARγ were identified across 24 weeks of feeding." (PMID 33817571, 2021).
Hypopharyngeal squamous cell carcinoma (1 paper, 2024). "The positive role of the PDK1/Notch axis in promoting metastasis through EMT activation in Hypopharyngeal squamous cell carcinoma (HSCC) has been recently emphasized." (PMID 38351531, 2024).
intraepithelial neoplasia (1 paper, 2025). A precancerous neoplastic process that affects the squamous, glandular, or transitional cell epithelium without evidence of invasion. "KRAS mutations lead to constitutive activation of the RAS protein, resulting in activation of the RAF/MEK/ERK pathway or PI3K/PDK1/AKT/mTOR pathway and, ultimately, the development of intraepithelial neoplasia." (PMID 39941707, 2025).
iron deficiency (1 paper, 2023). "In particular, iron deficiency is able to induce the up-regulation of LDH expression and a series of glycolytic enzymes, including pyruvate dehydrogenase kinase 1 (PDK1), the LDH isoenzyme, and GAPDH." (PMID 37887373, 2023).
keloid (1 paper, 2020). An irregularly shaped, elevated mark on the skin caused by deposits of excessive amounts of collagen during wound healing. "Since PDK1 and GLUT1 are PKM2-targeted genes, we subsequently analyzed expression of PKM2 in keloid tissue, which was upregulated relative to normal skin (7.58 vs. 0.29, P < 0.001)." (PMID 32750036, 2020).
laryngeal squamous cell carcinoma (1 paper, 2019). A squamous cell carcinoma that arises from the larynx. "For example, MiR-613 suppressed laryngeal squamous cell carcinoma progression through regulating PDK1." (PMID 31019537, 2019).
lentivirus infection (1 paper, 2018). Virus diseases caused by the Lentivirus genus. "In addition, PDK1 overexpression cells (PDK1) were established by lentivirus infection in MCF-7 cells." (PMID 29106390, 2018).
liver fibrosis (1 paper, 2017). "Because PI3K/Akt signaling pathway is vital for liver fibrosis, we next examined whether Tβ4 could regulate the expression of p-Akt, PDK1 and P70S6." (PMID 28978161, 2017).
lymphocytic leukemia (1 paper, 2016). "In lymphocytic leukemias, metabolic enzymes related with lipid biosynthesis, such as lipase A (LIPA) and pyruvate dehydrogenase lipoamide kinase isozyme 1 (PDK1), are targets of miR-125b." (PMID 27551267, 2016).
lymphoid tumors (1 paper, 2025). "Selective inhibition of PKCα/β, Chk1, and PDK1 promotes tumor cell death, while prednisone alleviates UCN‐01‐related inflammatory responses through immune regulation and enhances targeting of lymphoid tumors." (PMID 41244006, 2025).
mantle cell lymphoma (1 paper, 2018). Mantle cell lymphoma is a rare form of malignant non-Hodgkin lymphoma affecting B lymphocytes in the lymph nodes in a region called the ``mantle zone''. "Previously, edelfosine has been shown to inhibit PI3K/Akt survival pathway by displacing Akt as well as key regulatory kinases p-PDK1 (phosphatidylinositol-dependent protein kinase 1), PI3K and mTOR from lipid rafts in mantle cell lymphoma cells." (PMID 30399177, 2018).
memory impairment (1 paper, 2026). "Pdk1 icKO mice exhibited severe deficits in hippocampal oligodendrocyte (OL) maturation, myelination, and excitatory synaptogenesis, accompanied by impaired neuronal activation and profound memory impairments." (PMID 41980417, 2026).
meningioma (1 paper, 2018). A generally slow growing tumor attached to the dura mater. "AKAP12 seems to downregulate the AKT pathway by inactivating PDK1 Ser241, and IKKα Thr23 in meningiomas." (PMID 29391485, 2018).
metastasis (1 paper, 2021). The spread or migration of cancer cells from one part of the body (where they first appeared) to another. "Besides, high LDHA/PDK1 mRNA was found in OS tumors from patients with shorter overall survival, advanced TNM stages, and lymph node metastasis." (PMID 33962616, 2021).
metastatic prostate carcinoma (1 paper, 2021). A carcinoma that arises from the prostate gland and has spread to other anatomic sites. "Further, developing inhibitors against PDK1 may provide a novel strategy to inhibit the progression of metastatic prostate cancer." (PMID 34298795, 2021).
microcephaly (1 paper, 2017). A congenital or acquired developmental disorder in which the circumference of the head is smaller than normal for the person's age and sex. "Recent work showed that conditional deletion of PDK1 through GFAP-Cre mediated gene recombination causes microcephaly in mice, indicating a critical role of PDK1 in brain development." (PMID 29104535, 2017). "A conditional knock-in mouse model expressing the PDK1 L155E mutation displays microcephaly as well." (PMID 29104535, 2017).
myocardial ischemia (1 paper, 2025). A disorder of cardiac function caused by insufficient blood flow to the muscle tissue of the heart. "Furthermore, recent research has identified key roles for the pyruvate dehydrogenase kinase 1 (PDK1)/Akt-GSK3β-mPTP pathway and the AARS2-PKM2 metabolic axis in regulating this metabolic shift during myocardial ischemia." (PMID 41403700, 2025).
Nephropathy (1 paper, 2015). A nonspecific term referring to disease or damage of the kidneys. "PDK1 was also downregulated in the glomeruli of patients with T2D who did not yet have clinical nephropathy and after treatment with high glucose." (PMID 25950482, 2015).
paroxysmal AF (1 paper, 2022). "In a canine model, paroxysmal AF increased the lactic acid content and the expressions and activities of PDK-1, PDK-4, and LDHA and the decreased the expressions of PDH and citrate synthase and the AMP/ATP ratio in canine LA." (PMID 36139490, 2022). "The protein expression and activity of PDK-1 and PDK-4, which inactivate the PDH complex in the mitochondria, were increased and accompanied by a significant downregulation of PDH in canine models of paroxysmal AF." (PMID 36139490, 2022).
polycystic kidney disease (1 paper, 2021). A usually autosomal dominant and less frequently autosomal recessive genetic disorder characterized by the presence of numerous cysts in the kidneys leading to end-stage renal failure. "Case 7 is a girl born at full-term gestation with tuberous sclerosis complex and polycystic kidney disease caused by a deletion in 16p encompassing the TSC2 and PDK1 genes." (PMID 34149382, 2021).
polycystic ovary syndrome (1 paper, 2023). A disorder that manifests as multiple cysts on the ovaries. "Melatonin can enhance PDK1/Akt or PINK1/Parkin signaling in granulosa cells in polycystic ovary syndrome (PCOS) patients to alter the expression levels of the SIRT1 gene, thereby regulating mitochondrial function." (PMID 37239427, 2023).
psoriasis (1 paper, 2021). An autoimmune condition characterized by red, well-delineated plaques with silvery scales that are usually on the extensor surfaces and scalp. "PDK1 is also hyperactivated in IMQ-psoriasiform skin lesions, thus suggesting a relevant role for PI3Kδ/PDK1/p-AKT Thr308 axis in epidermal hyperplasia of IMQ-psoriasis like model." (PMID 34685616, 2021).
Stroke (1 paper, 2017). Sudden impairment of blood flow to a part of the brain due to occlusion or rupture of an artery to the brain. "There was a trend for GSK360A to increase 5 hour PDK-1 and also a trend for GSK360A to increase in both vehicle and GSK360A post-stroke HO-1 (not significant; data not shown)." (PMID 28880966, 2017).
urothelial carcinoma (1 paper, 2017). A malignant neoplasm derived from the transitional epithelium of the urinary tract (urinary bladder, ureter, urethra, or renal pelvis). "The regulation of S6K by 3-phosphoinositide dependent protein kinase-1 (PDK-1) may explain the difference in inhibition of p-mTOR and p-S6 status as demonstrated after rapamycin treatment in urothelial carcinoma." (PMID 29100343, 2017).
uveal melanoma (1 paper, 2014). A melanoma derived from melanocytes of the uveal tract. "This is also supported by a previous study which shows that exposure to low oxygen tension increases migration, invasion and adhesion of Mum2B uveal melanoma cells, activating the expression of CXCR4, angiopoietin-related protein, and pyruvate dehydrogenase kinase 1 in a HIF-1-dependent manner." (PMID 25166211, 2014).
vascular dementia (1 paper, 2019). A degenerative vascular disorder affecting the brain. "This study was focused on observing the neuroprotective effect of Naomaitai on the vascular dementia of rat and exploring the action mechanism of PI3K/PDK1/AKT signaling pathway." (PMID 30867669, 2019). "Naomaitai can ameliorate brain damage in rats with vascular dementia, inhibit neuronal apoptosis, and have anti-inflammatory and antioxidative stress effects, which may be regulated by the PI3K/PDK1/AKT signaling pathway." (PMID 30867669, 2019). "Furthermore, we found Naomaitai inhibited PI3K and PDK1 expression and activated phosphorylated AKT protein in rats with vascular dementia." (PMID 30867669, 2019).
vitiligo (1 paper, 2025). Generalized well circumscribed patches of leukoderma that are generally distributed over symmetric body locations and is due to autoimmune destruction of melanocytes. "As a compensatory mechanism for energy production, some glycolytic enzymes (hexokinase 2, HK2; pyruvate dehydrogenase kinase 1, PDHK1; pyruvate kinase M2, PKM2) are upmodulated in vitiligo melanocytes." (PMID 41007740, 2025).
wasting syndrome (1 paper, 2014). "Taken in conjunction with levels of Me1 and Pdk1, it appears that AHR-less-active animals may preferentially utilize nitrogenous molecules as sources of energy and that this preference may somehow confer a protective effect against TCDD-induced wasting syndrome." (PMID 25467400, 2014).
tumor (454 papers, 2006 to 2026). "Meanwhile, PDK1 can inhibit cell apoptosis, and silencing PDK1 can reduce NF-kappaB pathway, thereby weakening anti-apoptotic signals and making tumor cells more susceptible to programmed cell death." (PMID 40971960, 2025). "The upregulation of the LDH-A and PDK-1 genes has been associated with increased metastatic potential and their expression is essential for tumor growth and the establishment of malignant phenotype." (PMID 40551171, 2025). "Elevated levels of PDK1 expression have been implicated in tumour progression, metastasis, and the development of resistance to chemotherapy." (PMID 39625183, 2024). "Our studies collectively identify a novel mechanism promoting PDK1 protein expression and further advance our knowledge of the molecular mechanism underlying the tumor-promoting activity of MAPK4, an emerging novel therapeutic target for human cancers." (PMID 37531320, 2023). "Mounting evidence has indicated that PDK-1 is dysregulated in some malignancies and is associated with tumour proliferation, metastasis and poor prognosis." (PMID 36611209, 2023). "As an essential glycolytic enzyme, pyruvate dehydrogenase kinase 1 (PDK-1) promotes the Warburg effect in tumor cells and reduces cell damage caused by the accumulation of reactive oxygen species (ROS)." (PMID 36611209, 2023). "Pathologically, tumor patient-associated PDK1 mutations, either attenuating S6K1-mediated PDK1 phosphorylation or impairing PDK1 interaction with 14-3-3, result in elevated AKT kinase activity and oncogenic functions." (PMID 35318320, 2022). "PDK1 expression was significantly higher in the HER2-positive mutated tumours compared to the HER2-positive wildtype tumours (p = 0.0002)." (PMID 33933113, 2021). "We found that ARNT and PDK1 deficiency prevented apoptosis in tumor cells that were deprived of glucose, which indicates that the glycolytic switch from aerobic glycolysis to oxidative phosphorylation is essential for cell survival during metastasis." (PMID 33446631, 2021). "Intriguingly, CCCP and NAC dramatically inhibited ARNT and PDK1 deficiency-induced tumor cell extravasation in mouse models." (PMID 33446631, 2021). "In UBUC cohorts, T stage, lymph nodes metastases, high tumor grade, vascular invasion, peri-neural invasion, high mitotic rate, PDK1, and PDK3 overexpression were significantly associated with poor prognostic factors for DSS and MFS in univariate analysis." (PMID 34589439, 2021). "Accumulating evidence has shown that PDK1-3 are closely associated with the metabolism of tumor cells because they can phosphorylate PDC, leading to the inactivation of PDC 8-13." (PMID 32489458, 2020). "When these mice were crossed with tumourigenic heterozygous PTEN+/− mice, the prevalence of tumour development was reduced in mice with deficient PDK1 levels, confirming the importance of PDK1 in tumour development driven by loss of PTEN." (PMID 31088502, 2019). "The re-expression of PDK1 also significantly rescued the tumor growth phenotype caused by overexpression of Chibby in β-catenin-overexpressed cells." (PMID 29764469, 2018). "We next assessed mRNA and protein expression of PTEN and PDK1, respectively, in MM cell lines because PDK1 inhibition had been shown to be fail to prevent tumor growth in PTEN-deficient animal models." (PMID 28402933, 2017). "To understand the molecular mechanisms underlying DIC-induced tumor inhibition, we first measured the protein levels of PDK1, PDHA1, and p-PDHA1 in xenografts by western blot." (PMID 28617852, 2017). "This correlated with down-regulation of hypoxia inducible factor-1α (HIF-1α) and pyruvate dehydrogenase kinase-1 (PDK-1), both of which are associated with tumor survival/progression." (PMID 27775600, 2016). "The clinical data of 101 patients with GBC were retrospectively analyzed, and we found that the overexpression of PDK1 was associated with tumor differentiation, T stage, TNM stage, lymphatic invasion, and venous invasion (p < 0.05)." (PMID 26318166, 2015).
tumor (continued). "We demonstrated that PGE2 increased normal bronchial epithelial cell proliferation through induction of PDK1, an ankyrin repeat-containing Ser/Thr kinase implicated in the induction of apoptosis and the suppression of tumor growth." (PMID 26684827, 2015). "While both cytoplasmic and nuclear PDK1 are able to induce tumor formation, nuclear PDK1 is associated with higher-risk tumors than cytoplasmic PDK1." (PMID 25918701, 2015). "These mice were crossed with tumorigenic heterozygous PTEN +/- mice and the resulting mice with deficient PDK1 levels had a reduced prevalence of tumor development." (PMID 24739482, 2014). "GLUT-1 and PDK-1 expression was significantly associated with tumor progression, although only PDK-1 expression was an independent prognostic factor for patients who received 5-FU adjuvant treatment." (PMID 23135628, 2013). "Our observation also supports recent genetic PDK1 knock-down studies in PTEN deficient mouse tumor models showing only marginal effects on Thr308 phosphorylation." (PMID 22039492, 2011). "It has been implicated in tumor promotion and in the regulation of 3-phosphoinositide-dependent kinase-1 (PDK1)." (PMID 21297860, 2011). "PDK1 is a pivotal glycolytic enzyme linked to tumor proliferation and metastasis." (PMID 38671369, 2024). "Overall, their data showed that miR-194 acts as a tumor suppressor in colorectal carcinogenesis by targeting the PDK1/AKT2/XIAP pathway and could be an important diagnostic and prognostic biomarker for CRC43." (PMID 36854781, 2023). "Moreover, higher PDK1 expression is associated with advanced tumor stage (positive lymph node metastasis or high histological grade) and shorter overall survival." (PMID 34789718, 2021). "Pyruvate dehydrogenase kinase 1 (PDK1), as a key regulatory enzyme implicated in metabolic reprogramming of tumors, abnormally high expressed in various tumors and involved in the regulation of tumor cell biological behavior." (PMID 33403023, 2021). "In MIBC, PDK1 expression was linked to a high tumor grade and a high Ki67 index in one study." (PMID 34589439, 2021). "Therefore, the inhibition of Akt and PDK1 is considered a prominent strategy in tumor settings associated with hyperactivation of the PI3K/mTOR pathway." (PMID 31683659, 2019). "Moreover, PDK1 tumor-to-normal expression ratios were associated with the OS of GBC patients (p < 0.05)." (PMID 26318166, 2015). "The transforming ability of PDK1 in vitro and in vivo is mediated by PKCα and is linked to c-myc function and the expression of caveolin-1, an integral protein component of caveolae known for its role as a tumour suppressor." (PMID 18349831, 2008). "Aberrant activation of PDK1 facilitates tumor initiation, progression, and therapeutic resistance in various cancer types." (PMID 41928774, 2026). "In breast cancer tissues, there is an abnormal overexpression of PDK1 (key enzyme in the glucose metabolism pathway) promote tumor growth and metastasis." (PMID 40689201, 2025). "We designed a total of 22 PDK1 degrader compounds and identified the top‐performing compound, A04, which demonstrates long‐lasting PDK1 degradation and potent anti‐tumor activity." (PMID 40873633, 2025). "E2 and E5 (novel SK derivatives) disrupted tumor glycolysis and induced apoptosis by specifically targeting PDK1." (PMID 40689201, 2025). "GO and KEGG analysis showed that PDK1 and its highly positively correlated genes also promote tumor progression." (PMID 40971960, 2025). "The tumor sections were also stained for PDK1 and CAIX, which revealed higher expression of both markers in the 4T1 tumors in contrast to 67NR ones." (PMID 40551171, 2025).